SBDS (SBDS ribosome maturation factor)
Diseases named in the same sentence as SBDS in open-access papers (continued):
Sharing a sentence is not in itself a finding about the gene and the disease.
lung carcinoma (3 papers, 2020 to 2025). "A large-scale study of 17,904 Chinese lung cancer patients identified SBDS as the most frequently mutated gene among cancer-susceptibility genes, with a prevalence of 1.37%." (PMID 41155398, 2025). "The SBDS c.184A>T (p.Lys62*) pathogenic variant demonstrated a significant association with increased lung cancer risk, showing an odds ratio of 4.8 in case–control analysis compared to the gnomAD East Asian population." (PMID 41155398, 2025). "SBDS p.K62* truncation variant is more common in East Asia population (0.033% of AF) than European population (0.015%), and in our lung cancer cohort, the AF of the variant was as high as 0.156%." (PMID 37885353, 2024). "Unexpectedly, two genes which are seldom reported to link to lung cancer risk, SBDS and TSHR, had the highest prevalence in our cohort." (PMID 37885353, 2024). "It seems that the P/LP germline variants of SBDS not only increase the risk of myeloid malignancy, but also may increase the risk of solid tumors like lung cancer; however, the conclusion needs other studies to validate and the underlying mechanisms also need experimental studies to illustrate." (PMID 37885353, 2024). "Case–control analysis showed SBDS c.184A>T(p.K62*), TSHR c.1574T>C(p.F525S), BRIP1 (BRCA1 interacting helicase 1) c.1018C>T(p.L340F), and MUTYH (mutY DNA glycosylase) c.55C>T(p.R19*) were significantly associated with increased lung cancer risk (q value < 0.05)." (PMID 37885353, 2024).
myelodysplastic syndrome (3 papers, 2017 to 2019). A clonal hematopoietic disorder characterized by dysplasia and ineffective hematopoiesis in one or more of the hematopoietic cell lines. "SBDS is inactivated by mutations in the human Shwachman–Bodian–Diamond syndrome, featuring skeletal abnormalities, bone marrow failure and susceptibility to developing myelodysplastic syndrome and secondary AML." (PMID 27436341, 2017). "Importantly, decreased expression of Dicer1 was detected in MSC-derived osteoprogenitors from myelodysplastic syndrome (MDS) patients, along with a reduction of the SBDS gene." (PMID 31861268, 2019).
acute myelogeneous leukemia (2 papers, 2022 to 2026). "Among them, two cases carried pathogenic compound heterozygous mutations (c.258+2T>C and c.184A>T) in SBDS, presenting with the phenotype of acute myeloid leukemia (AML) with dysplastic malformation syndrome or bone marrow dysgenesis." (PMID 41472573, 2026).
breast tumor (2 papers, 2019 to 2025). "Also, the results show that SBDS gene can be used as a negative control at in vitro model systems, since the gene was completely unmethylated in primary tumor tissue of breast and cultured breast tumor cells." (PMID 30792990, 2019).
cervical cancer (2 papers, 2020 to 2023). A primary or metastatic malignant neoplasm involving the cervix. "Knockdown of SBDS by short hairpin RNA in cervical cancer HeLa cells and TF-1 myeloid cells showed that decreased SBDS expression is associated with increased release of ROS." (PMID 37627314, 2023).
colon cancer (2 papers, 2020 to 2022). "In cancer cases, all colon cancer cases were affected by pathogenic variants in MLH1 and SBDS genes, while 20% (2/10) of the thyroid cancer cases by RET c.1900T>C variants were affected." (PMID 36428697, 2022). "To determine whether SBDS has a tumor-suppressive role, we first performed flow cytometry analysis of colon cancer cells after overexpression of SBDS." (PMID 32198344, 2020).
hepatocellular carcinoma (2 papers, 2023 to 2024). A malignant tumor that arises from hepatocytes. "SBDS plays important roles in the development of hepatocellular carcinoma." (PMID 39217359, 2024).
Alzheimer disease (1 paper, 2022). A progressive, neurodegenerative disease characterized by loss of function and death of nerve cells in several areas of the brain leading to loss of cognitive function such as memory and language. "For example, we found that levels of ADAR, XRCC6 and SBDS were reduced in 5 of 7 Alzheimer’s disease samples and levels of DDX5, U2AF2, ILF3 were reduced in 4 of 7 Alzheimer’s disease NPC vasculature samples by greater than 50%." (PMID 36196083, 2022).
campomelic dysplasia (1 paper, 2021). "In this respect, it is tempting to speculate on the classification of campomelic dysplasia (OMIM #114290), as links between Sox9 and genes involved in ribosomopathies were identified in the present work (SBDS, Rpl11, and Rps26)." (PMID 34235151, 2021).
colorectal cancer (1 paper, 2020). A primary or metastatic malignant neoplasm that affects the colon or rectum. "We also performed colorectal cancer tissue array analysis and found that SBDS is significantly overexpressed in colorectal cancer versus adjacent normal tissues." (PMID 32198344, 2020).
endometriosis (1 paper, 2025). The growth of functional endometrial tissue in anatomic sites outside the uterine body. "Furthermore, the identification of upregulated genes, such as SIRT1, SBDS, SRF, SPN, P2RX1, TEAD3, and SLITRK3, alongside downregulated genes, including KIF22, KIF25, GAS2L2, and HINT3, highlights a broad transcriptional reprogramming within endometriosis-affected tissues." (PMID 41516028, 2025).
Fanconi anemia (1 paper, 2025). Fanconi anemia (FA) is a hereditary DNA repair disorder characterized by progressive pancytopenia with bone marrow failure, variable congenital malformations and predisposition to develop hematological or solid tumors. "Heterozygous mutations in Fanconi anemia genes predispose AA and MDS patients to BMF and leukemogenesis, and heterozygosity for the 258 + 2 T >C SBDS mutation appears to be another genetic factor accelerating telomere shortening in aAA patients." (PMID 41188636, 2025).
gastric cancer (1 paper, 2023). A primary or metastatic malignant neoplasm involving the stomach. "Here, we provide additional evidence supporting its tumor suppressor function; that is, an SBDS germline truncating variant was detected in a 20‐year‐old gastric cancer patient, and no other PGV in the same patient was identified." (PMID 37610374, 2023).
Intellectual disability (1 paper, 2018). "Some of the symptoms caused by mutations in SBDS and FAM120C, such as short stature and intellectual disability, are similar to shown in our patient." (PMID 30598092, 2018).
Klinefelter syndrome (1 paper, 2025). A sex chromosome disorder caused by the presence of an extra X chromosome in the male karyotype. "We present a rare case of SDS resulting from a homozygous in the SBDS gene, co-occurring with mosaic 47,XXY/46,XY Klinefelter syndrome." (PMID 41383570, 2025).
Metaphyseal dysplasia (1 paper, 2012). The presence of dysplastic regions in metaphyseal regions. "Subsequent testing revealed the presence of fat globules in stools, reduced faecal chymotrypsin, fat-soluble vitamin deficiency, metaphyseal dysplasia on skeletal survey and heterozygous mutations of the SBDS gene." (PMID 22554078, 2012).
myeloid leukemia (1 paper, 2009). A clonal proliferation of myeloid cells and their precursors in the bone marrow, peripheral blood, and spleen. "We observed that SBDS RNA and protein are expressed in the human myeloid leukemia PLB-985 cell line and in human hematopoietic progenitor cells by quantitative RT-PCR and Western blot analysis." (PMID 19759903, 2009). "Here we show that SBDS expression is downregulated during neutrophil differentiation in the human myeloid leukemia cell line PLB-985 and in clinically relevant human primary CD34+ hematopoietic progenitor cord blood differentiation cultures." (PMID 19759903, 2009).
myeloid malignancies (1 paper, 2024). "On the other hand, patients with SDS have an increased risk of developing myeloid malignancies and clonal hematopoiesis caused by mutations bypassing or alleviating intrinsic fitness caused by SBDS mutation." (PMID 39314632, 2024).
myopia (1 paper, 2024). "In one (1/18) child, we found genetic variants defined as VUS, and in four (4/18) children, we found (likely) pathogenic variants in the genes TRPV4, TUBA1A, SBDS, KIDINS220, which have not been previously associated with the development of myopia." (PMID 39495751, 2024). "It is also worth noting that our study describes cases of HM in individuals with variants in genes that have not yet been clearly associated with the development of myopia (TRPV4, TUBA1A, SBDS, KIDINS220)." (PMID 39495751, 2024).
neuroblastoma (1 paper, 2022). Neuroblastoma (NB) is the most common solid, extracranial childhood tumor. "Additionally, clinically relevant germline variants were detected in four cancer-associated genes, including an SBDS splice-site mutation (c.258 + 2T > C) in a rhabdomyosarcoma, BARD1 p.E652fs*69 in a neuroblastoma, EP300 p.A2259fs*20, and EXT2 p.W414* in two osteosarcoma patients." (PMID 35585047, 2022).
Sepsis (1 paper, 2025). Sepsis is defined as life-threatening organ dysfunction caused by a dysregulated host response to infection.
viral infection (1 paper, 2023). "To determine whether loss of SBDS or SPATA5 directly contributed to impaired viral infection, we reconstituted CRISPR-targeted cells with cDNAs expressing CRISPR-resistant versions of each host factor gene or firefly luciferase (Fluc) as a control." (PMID 36809113, 2023).
cancer (12 papers, 2015 to 2024). A tumor composed of atypical neoplastic, often pleomorphic cells that invade other tissues. "The seven hub RBPs CD3EAP, POP5, NOP10, ATXN1, ZC3H12C, RBPMS, and SBDS were implicated in the progression and prognosis of many cancers." (PMID 36262474, 2022). "SBDS is often overexpressed or amplified in human cancers, and high endogenous SBDS are significantly associated with adverse prognoses." (PMID 36262474, 2022). "In the present study, we found that upregulation of SBDS is associated with unfavorable prognosis in a broad spectrum of human cancers." (PMID 32198344, 2020). "SBDS was highly expressed in a broad range of human cancers and significantly associated with poor prognosis of these cancers." (PMID 32198344, 2020). "We found that SBDS is highly expressed in human cancers, and its high level is inversely associated with the survival rate of patients as an unfavorable prognostic factor." (PMID 32198344, 2020). "The Shwachman-Bodian Diamond syndrome (SBDS)-associated gene, SBDS, is involved in rRNA synthesis and ribosome maturation, but the role of SBDS in cancer is largely elusive." (PMID 32198344, 2020). "Because the incidence of SBDS germline mutation is rare, ~1 in 50,000 births, the role of SBDS mutations in cancer development among a wider population remains largely obscure." (PMID 32198344, 2020). "Hence, our study demonstrates underappreciated dual functions of the SDS-associated protein, SBDS, in cancer development and underscores its potential clinical significance in cancer therapy." (PMID 32198344, 2020). "It remains unclear if and how the SDS-associated gene SBDS has a role in cancer development." (PMID 32198344, 2020). "We show that knockdown of the ribosomopathy factor SBDS, or of key ribosome biogenesis factors (PPAN, NPM, PES1) is associated with enhanced levels of ATG7 in cancer cells." (PMID 34944838, 2021). "By mining the Oncomine database, we found that SBDS is upregulated in multiple human cancers compared with the normal tissues." (PMID 32198344, 2020). "In this study, we found that SBDS is often overexpressed or amplified in human cancers, and high level of endogenous SBDS is significantly associated with unfavorable prognosis." (PMID 32198344, 2020). "SBDS is essential for ribosome assembly in cytoplasm and rRNA synthesis in nucleolus, which may confer its oncogenic action in cancer." (PMID 34291084, 2021). "In addition, the TCGA database showed that SBDS is preferentially upregulated or amplified in all types of cancers examined." (PMID 32198344, 2020).
cancer (continued). "Therefore, we assumed that the upregulation of apoptosis through SBDS knockdown could facilitate the drug accessibility to the cancer cells in the stiff substrates." (PMID 31853379, 2019). "In addition, half of these cases (4/8) also carried the SBDS (ENST00000246868.2: c.258+2T>C) variant, while two cases without a cancer diagnosis only carried the heterozygous SBDS c.258+2T>C variant." (PMID 36428697, 2022). "Interestingly, the SBDS transcript level of cells in the stiff substrates was exclusively upregulated in two cancer cell lines, but not in the normal cell line." (PMID 31853379, 2019).
tumor (10 papers, 2019 to 2025). "Using CRC TMA sections, it has been shown that SBDS is overexpressed in tumor cells compared to normal adjacent cells and high SBDS expression is associated with an unfavorable prognosis." (PMID 33120992, 2020). "The results showed tumor-specific mutations such as missense mutation in exon 9 of PIK3CA P. e542k and germline genes mutations of PRF1, SBDS, and a tumor mutation burden of 12.89 mutations/Mb." (PMID 36930086, 2023). "In line with the cell-based results, the xenograft tumor growth was significantly inhibited by ectopic expression of SBDS as compared to the control group, whereas the body weights were not markedly affected." (PMID 32198344, 2020). "Consistently, ablation of SBDS by shRNAs more drastically induced tumor cell growth arrest in HCT116p53+/+ cells than that in HCT116p53−/− cells." (PMID 32198344, 2020). "Interestingly, ectopic SBDS in the nucleoplasm also suppresses tumor cell growth and proliferation in vitro and in vivo." (PMID 32198344, 2020). "Compared to normal samples, ATXN1, RBPMS, SBDS, and ZC3H12C were downregulated, and CD3EAP, NOP10, and POP5 were upregulated in UCEC tumor samples." (PMID 36262474, 2022). "CD3EAP, NOP10, and POP5 were significantly up-regulated in tumor tissue samples, while ATXN1, RBPMS, SBDS, and ZC3H12C were significantly downregulated in tumor tissue samples calculating by DESeq2 and edgeR, which were consistent with our previous results." (PMID 36262474, 2022). "Then these two types of tumor tissues and their 2D and 3D cultures were investigated for changes considering methylation levels in PAX5, TMPRSS2, and SBDS genes using real-time polymerase chain reaction." (PMID 30792990, 2019). "Ectopic SBDS did not influence the mouse body weights, xenograft tumor volumes or sizes dramatically." (PMID 32198344, 2020). "The primary objective of our study is to determine whether primary tumor tissue and cultured tumor cells in 2D and 3D tissue culture systems have the same methylation signature for PAX5, TMPRSS2, and SBDS." (PMID 30792990, 2019). "The differences between cells grown in 2D-3D cultures and primary tumor tissues were statistically nonsignificant (P>0.05) for SBDS gene." (PMID 30792990, 2019). "We also investigated whether PAX5, SBDS, and TMPRSS2 could be used as biomarkers by evaluating the stability of primary tumor cells grown in 2D or 3D culture media." (PMID 30792990, 2019). "For this purpose, our first aim was to cultivate the tumor cells in 2D and 3D tissue culture systems and to determine whether the primary tumor tissue and cultured cells in 2D and 3D tissue culture systems had the same methylation signature for PAX5, TMPRSS2, and SBDS." (PMID 30792990, 2019).